BECN1 (beclin 1)
Diseases named in the same sentence as BECN1 in open-access papers (continued):
Sharing a sentence is not in itself a finding about the gene and the disease.
cancer (continued). "Because whole‐body knockout of essential Atg genes leads to perinatal lethality, whole‐body knockout strategies to study the role of autophagy in cancer are limited to heterozygous deletion models such as Becn1+/−, which achieves only partial autophagy incompetence." (PMID 34459017, 2021). "c-FLIPL-Beclin-1–autophagy axis investigation may therefore open novel interesting scenarios to be exploited in cancer therapy." (PMID 34238932, 2021). "Interestingly, an increase in Beclin 1 expression––as reflected by the percent cancer cells staining in the resected pancreatic specimen––correlated with a worsened PFS and OS." (PMID 34559451, 2021). "In addition, the inhibition of autophagy in cancer cells using siRNA against Beclin 1 (siBCN1) decreases cell survival induced by OP9 Dif, showing that autophagy promotion by adipocytes participates in the increase in cell survival." (PMID 34359819, 2021). "Moreover, decreased expression of BECN1 was observed in other kinds of cancer, including colon, brain and cervical ones." (PMID 33804163, 2021). "Ovarian carcinoma patients with a high expression of Beclin-1 were found to have a better prognosis, suggesting that autophagy might limit cancer progression." (PMID 33743781, 2021). "Beclin-1 induces autophagy leading to survival promotion and maintenance of cancer stem cells." (PMID 33452364, 2021). "The overexpression of 14‐3‐3ζ also up‐regulated the mRNA expression of BECN1 gene in cancer cells." (PMID 31709727, 2020). "This is further evidence of the role of beclin-1 and autophagy play in cancer." (PMID 32998777, 2020). "BECN1 is silenced in cancer tissue, which indicates that DNA methylation may also be responsible for this mechanism." (PMID 33322704, 2020). "It was revealed that AKT could mediate Beclin 1 phosphorylation to form a filament complex as an autophagy inhibitory in human cancer." (PMID 32760250, 2020). "In liver tumorigenesis, Beclin 1, a haplo-insufficient gene has been implicated, similarly, ATG 5, ATG7 and p62 are also found to have important tumorigenic role, and suppression of these genes can reduce cancer progression." (PMID 33311531, 2020). "Among mammal ATG proteins, Beclin-1, ATG5, ATG7, ATG12, ATG16L1 and LC3B are the most studied with respect to inflammation, and defects in autophagy are linked to many inflammatory diseases and cancer." (PMID 31969156, 2020). "For instance, several studies demonstrated that Beclin-1 is a potent biomarker in several cancers." (PMID 32245178, 2020). "In TCGA data, Becn1 expression was higher in male than female cancer patients (P<0.05)." (PMID 33425768, 2020). "We point out a potentially unique role for Atg7, as neither chemical inhibition with Chloroquine nor loss of Beclin-1 or Atg12 induced cancer cell death, even though autophagy signaling was reliably blocked." (PMID 32046105, 2020). "Thus, the goal of this mini-review is to compile the data available regarding the autophagy regulation through Beclin 1 tyrosine phosphorylation in cancer." (PMID 33287140, 2020). "Interestingly, an intricate link between autophagy and cancer is established when Beclin 1 (BECN1), an essential autophagy gene, is found to suppress breast tumorigenesis." (PMID 32935427, 2020). "To date, many concerns need to be still overcome, to fully clarify the ultimate role of Beclin-1 expression in cancer progression and cancer response to therapy in UM, and a further study on larger, multi-institutional series of cases is currently in progress to definitively validate our results." (PMID 33330070, 2020). "Similarly, Beclin-1 is an important autophagosome initiation tumor suppressor protein, whose expression is reduced in many cancers." (PMID 30669284, 2019).
cancer (continued). "The dysfunction of BECN1 has been suggested in many diseases, including cancer." (PMID 31272261, 2019). "In addition, the cleavage of Beclin-1 mediated by caspase has been shown to induce crosstalk between autophagy and apoptosis, and Beclin-1 dysfunction has been reported in disorders such as cancer and neurodegenerative diseases." (PMID 31336911, 2019). "So more studies need to be done to fully clarify the function of BECN1 in cancer cells." (PMID 31272261, 2019). "Although the relevance in cancer of the Beclin 1 phosphorylation/dephosphorylation by the DAPK-family members and PP2A needs to be explored, these data indicate a potential coordinated mechanism of S90 phosphorylation by multiple kinases including AMPK, MK2/3, and DAPK family members." (PMID 31877888, 2019). "This review will focus on the role of Beclin 1-dependent autophagy in cancer." (PMID 31877888, 2019). "In addition, there are BECN1-independent mechanisms of autophagy and autophagy-independent roles for BECN1 in cancer." (PMID 30370269, 2018). "Even though the functions of BECN1 can be simply represented as regulation of vacuolar protein sorting and autophagy, relevance of this signaling molecule encompass immunity, metabolism, and cancer." (PMID 30370269, 2018). "In some types of tumors, such as liver and lung cancer, Beclin-1 expression is reduced, indicating that autophagy may inhibit the development of these cancers." (PMID 30344951, 2018). "As beclin-1 is required for induction of autophagy, one might expect that treatment with a chemotherapeutic agent would result in increased beclin-1 expression, as was observed in our non-cancer cell lines." (PMID 30372478, 2018). "In addition, gossypol prevents the interaction between Bcl-2 and Beclin-1 at the endoplasmic reticulum, decreases the levels of Bcl-2 and increases Beclin-1 expression by inducing Beclin-1 Atg5-a dependent autophagic pathway in cancer cells." (PMID 30459622, 2018). "BECN1 was the first connection described between autophagy and cancer." (PMID 30344951, 2018). "It has been reported that LC3-II and Beclin-1 are prognostic factors of various human cancers." (PMID 30013454, 2018). "Moreover, in tumors of the gastrointestinal tract, increased expression of BECN1 has been observed in the first stages of the disease, while Beclin-1 activity is reduced in subsequent stages of cancer progression." (PMID 30344951, 2018). "In addition, AT-101 was shown to prevent the interaction between Bcl-2 and Beclin-1 at the endoplasmic reticulum, to decrease the levels of Bcl-2 and to increase Beclin-1 expression by inducing Beclin-1 Atg5-dependent autophagic pathway in cancer cells." (PMID 30459622, 2018). "In addition, several studies have shown that the level of Beclin 1 is decreased in various cancers, such as cervical squamous-cell carcinomas and hepatocellular carcinomas." (PMID 30400561, 2018). "We found that knockdown of Beclin 1 resulted in prolonged accumulation of TAGs in cancer cells." (PMID 28151470, 2017). "These Beclin 1 mimetics might be promising tools for understanding the roles of Bcl-xL protein, Beclin 1, and even the multifaceted roles of autophagy in cancer development and drug resistance." (PMID 28881653, 2017). "Moreover, the expression of proteins involved in autophagy such as BECN1 (BECLIN-1), ATG5, UVRAG (UV radiation resistance-associated gene), GABARAP and LC3 has been described to be reduced or lost in several types of cancers." (PMID 28915569, 2017). "Beclin 1 has also been shown to be a promising prognostic marker for a variety of cancers." (PMID 28881721, 2017). "Another study demonstrated that silencing of beclin-1 or treatment with an autophagy inhibitor blocked obatoclax-mediated cell death in B-cell lymphomas, further highlighting the importance of autophagy activation in the anti-cancer effects of obatoclax." (PMID 28895911, 2017). "Beclin-1 was remarkably expressed in the cytoplasm of cancer cells." (PMID 28176874, 2017).
cancer (continued). "Collectively, these studies showed that the role of Beclin 1 in cancer prognosis and treatment might be tissue- and context-dependent." (PMID 28881721, 2017). "Thus, the genetic background of a cell determines which pathway is triggered, a death signals to regulate autophagy initiation between beclin-1/Bcl-2 interaction, and this provides new insight into cancer control and therapy." (PMID 29212215, 2017). "The role of autophagy in cancer therapy has been implicated to against cytotoxic, plenty of clinical trials have been launched targeting the inhibition of autophagy while the expression of autophagy-associated proteins, such as beclin-1 and LC3, are also connected with the poor prognosis of cancers." (PMID 28915616, 2017). "Beclin-1 has repeatedly been reported as a target for applied therapies because its low expression may be attributed to the development of human cancer." (PMID 27527160, 2016). "Indeed, in a study of a cohort of CRCs, nearly half of the cancers exhibited a significant nuclear Beclin-1 staining pattern." (PMID 27444698, 2016). "Indeed, in a previous study on CRCs, nearly half of the cancers exhibited a significant nuclear Beclin-1 staining pattern." (PMID 27444698, 2016). "In contrast to Beclin 1 that predicts better prognosis, in gastrointestinal cancers, upregulated LC3 expression partially correlates with the level of Ki-67, a proliferation index associated with the clinical courses of cancer." (PMID 26910278, 2016). "Results of our present study also demonstrated that tumors with stromal beclin 1 had higher carcinoma cell proliferation, which is also consistent with the hypothesis above." (PMID 26984766, 2016). "The prognostic role of Beclin 1 has been widely studied in various types of human cancers, and the patients’ outcomes determined by cytoplasmic Beclin 1 expression may be specific to the cancer type." (PMID 26506105, 2015). "Validation studies involved comparison of hereditary (n = 8) and sporadic (n = 18) cases of disease with the genes of interest being PIK3C3 (on the basis of the autophagy array data) and Beclin-1, which was selected given previously demonstrated importance in other cancer types." (PMID 25487826, 2015). "The nucleolar LC3B localization and the nuclear LC3A, LC3C and Beclin-1 accumulation found in the current study provide a basis for further studies on the distinct biological role these proteins may have in normal and cancer tissues." (PMID 26378792, 2015). "Moreover, chromatin immunoprecipitation and luciferase reporter analysis verified that c-jun, a target of JNK1, was activated and directly bound to the beclin-1 promoter in ceramide-treated cancer cells." (PMID 26622781, 2015). "Beclin 1 is also known to prevent the growth of malignant tumors." (PMID 25693418, 2015). "Beclin 1 established the first connection between autophagy and cancer." (PMID 26506105, 2015). "Targeting beclin-1 may be a novel therapeutic strategy to reverse the dysfunction of ER stress-induced autophagy in diseases, including cancer, neurodegenerative disease and diabetes mellitus." (PMID 26622781, 2015). "We propose that long-term AN usage might render tumors into a particular type of autophagy-addicted context distinct from other types of cancers with frequent downregulation of Beclin 1 and/or LC3 proteins." (PMID 26017803, 2015). "This suggests that drugs that enhance the addition of this phosphate group to Beclin 1 could help activate autophagy and have anti-cancer effects." (PMID 25693418, 2015). "Furthermore, recently many reports have shown that suppression of autophagy by silencing ATG7 and beclin 1 results in increase in ROS generation leading to sensitization of cancer cells to drug induced apoptosis." (PMID 24755562, 2014). "Among these genes, BECN1 (a mammalian homolog of the yeast ATG6 protein) is an essential modifier of the autophagic process and has been implicated in the tumorigenesis of many types of cancers." (PMID 24723943, 2014).
cancer (continued). "The expression of Beclin 1 and its roles in malignant tumors have drawn great interest." (PMID 24675697, 2014). "With regard to the pathological staging, it was found that of the 20 carcinomas with <20% of BECLIN 1-positive cells, 10 were classified as I-II stage and 10 as III-IV stage; of the 41 carcinomas with ≥20% BECLIN 1-positive cells, 24 were of I-II stage and 17 of III-IV stage." (PMID 25136588, 2014). "The deletion and reduced expression of Beclin-1 was found in various types of cancer cells." (PMID 23765161, 2013). "Beclin 1, a homologue for Apg6 and an important member of the initiation complex for autophagic machinery is reported to be mono-allelically deleted in several cancers." (PMID 24205125, 2013). "Furthermore, Beclin 1-dependent autophagic function has been shown to be suppressed in human cancer through activating AKT." (PMID 24260370, 2013). "Beclin-1 plays an important role in autophagy, differentiation and apoptosis of cancer cells." (PMID 23935917, 2013). "Indeed, Beclin 1 overexpression has been shown to increase anticancer drug-induced apoptosis in cervical cancer cells, thus sensitizing cancer cells to chemotherapeutic drugs." (PMID 23840208, 2013). "Overexpression of Beclin 1 has been reported in many cancers." (PMID 23029344, 2012). "Beclin 1 provided the first connection between cancer and autophagy." (PMID 22295229, 2011). "This trend was also found when assessing Beclin 1 expression in combination with HIF-1α, indicating that hypoxia-induced activation of Beclin 1 and autophagy may drive carcinoma cells to survive treatment and potentially lead to reoccurrence." (PMID 22190938, 2011). "In addition, HMG-I/Y is involved in c-Jun mediated anchorage-independent growth and the activation of c-Jun/JNK pathway can mediate Beclin 1 expression, which plays a key role in autophagic cell death in cancer cells." (PMID 20482821, 2010). "Since beclin 1 has important functions in apoptosis and autophagy, its epigenetic modification might provide new targets for cancer therapy." (PMID 20230646, 2010). "Exploring different involving factors that could affect the regulatory expression of beclin 1 might contribute to the pathogenesis of human cancers." (PMID 20230646, 2010). "Studies in cancer and neurodegeneration also support the relevance of Beclin 1 levels." (PMID 21217818, 2010). "The human beclin 1 gene contains a 1.5 kb CpG island from the promoter to part of the intron 2, suggesting that DNA methylation may be responsible for down-regulation of beclin 1 expression in cancer." (PMID 20230646, 2010). "Decreased levels of Beclin 1 are also seen in various cancer cells." (PMID 20454448, 2010). "Beclin-1+/− mice easily develop carcinoma, limiting their usefulness as a model." (PMID 18830406, 2008). "The absence of Beclin‐1 leads to autophagy inhibition, resulting in the dysregulation of cellular autophagy and an increased risk for various diseases such as neurodegenerative disorders, cancer, and infections." (PMID 40667723, 2025). "This suggests that Beclin-1 may act as a negative regulator of EMT in cancer cells." (PMID 38398197, 2024). "Hence, purposeful adjustment of Beclin-1 and autophagy could greatly increase cell mortality in human cancers." (PMID 39650649, 2024). "Hence, ATGs and Beclin-1 serve as dependable prognostic indicators in cancer." (PMID 39650649, 2024). "Future studies need to further investigate the specific mechanisms of Beclin-1 to develop more effective therapeutic strategies, particularly in personalized and combination therapies, which will help improve the survival rates and quality of life for cancer patients." (PMID 39650649, 2024).
cancer (continued). "Therefore, the prognostic effect of BECN1 may be due to its ability to confer chemoresistance to cancer cells." (PMID 36830954, 2023). "Furthermore, BECN1 heterozygous mice develop spontaneous cancers." (PMID 35409187, 2022). "Additionally, the BECN1 allelic loss is confounded by its location adjacent to BRCA1 on human chromosome 17q21, raising the possibility that loss of BECN1 in human cancers may be associated with the loss of BRCA1 in human breast and ovarian cancers." (PMID 36528652, 2022). "While mutations of autophagy genes (ATGs) are notably rare in cancer, haploinsufficiency network analyses across many cancers have shown that the autophagy pathway is frequently hit by somatic copy number losses of ATGs such as MAP1LC3B/ATG8F (LC3), BECN1/ATG6 (Beclin-1), and ATG10." (PMID 35681458, 2022). "In addition, CQ or BECN1-knockdown increased phosphorylation of eEF2 specifically under treatment of TGF-β1 not only in A549 but also in other types of cancer cells although this eEF2 phosphorylation at T56 varied among these cancer cells." (PMID 36230768, 2022). "Similarly, Fdb treatment with a suboptimal dose can reduce drug toxicity in both normal and cancer cells, but the cells showed a difference in their ability to induce the mediators of cell survival, such as Beclin-1 (anti-apoptosis), found downstream of mTOR and LC3B." (PMID 35323219, 2022). "Interactions of Beclin 1 with TM7SF2 may also have a significance in cancer-dependent autophagy." (PMID 34440098, 2021). "A recent study outlined that Beclin-1 may interact also with members of the bcl-2 protein, acting as a tumor suppressor protein, and this finding could explain, at least partially, its positive prognostic role in different types of human cancers." (PMID 33330070, 2020). "Nevertheless, the results of our study indicate that a relationship between the immunohistochemical expression of Beclin-1 and the biological behavior of UM exists, and this could open up new prognostic and therapeutic strategies for this peculiar, deadly malignant tumor." (PMID 33330070, 2020). "Moreover, the level of BECN1 is higher in cancer cells compared to normal cells." (PMID 33322704, 2020). "Thus, autophagy induction in these lung-derived cancer cell lines appears to be BECN1-independent." (PMID 31101821, 2019). "Several studies suggest that the BECN1 gene is not heavily mutated in cancer." (PMID 31877888, 2019). "However, the exact role of BECN1 in cancer progression is still obscure." (PMID 31272261, 2019). "Thus, our study demonstrated that BECN1 could promote cancer progression through facilitating cancer cell migration in NSCLC cells." (PMID 31272261, 2019). "It is well known that mTOR is the switch of the autophagic pathway, which could promote cancer cell apoptosis, and mTOR activation was suppressed by TSPf, while Beclin 1, another critical molecule in autophagy, was induced, we wondered whether TSPf could trigger the autophagic process." (PMID 29997504, 2018). "In addition, Beclin-1, involved in autophagy induction was increased by C26 cancer (p < 0.01)." (PMID 30713500, 2018). "Moreover, it was demonstrated that treatment of different cancer cell lines with the miR-30a mimic and antagomir molecules could respectively decrease and increase BECN1 expression." (PMID 28208686, 2017). "The elucidation of the systemic mechanisms of E3 enzymes involved in the regulation of BECLIN 1 will important to understand the complex interplay within the regulatory network of PtdIns3P-signaling in the occurrence of infections, neurodegenerative diseases and cancer." (PMID 29186924, 2017).